SOST (sclerostin)
Diseases named in the same sentence as SOST in open-access papers (continued):
Sharing a sentence is not in itself a finding about the gene and the disease.
dementia (4 papers, 2020 to 2026). Loss of intellectual abilities interfering with an individual's social and occupational functions. "DKK1 and sclerostin are bone-related factors showing promise as potential biomarkers for dementia prediction." (PMID 40700291, 2025). "Research into the effect of anti-sclerostin antibodies such as romosozumab on AD development and dementia progression in individuals with MCI will be helpful." (PMID 40700291, 2025). "Current evidence implicates DKK1 in the amyloid-induced toxicity that underpins AD progression and highlights the emergence of sclerostin as a bone-related biomarker with potential for early dementia detection." (PMID 40700291, 2025). "However, whether or not SOST plays an associative or causative role in vascular pathophysiology, and how this may influence development of dementia, remains unknown." (PMID 33424724, 2020).
Gaucher disease (4 papers, 2021 to 2025). Gaucher disease (GD) is a lysosomal storage disorder encompassing three main forms (types 1, 2 and 3), a fetal form and a variant with cardiac involvement (Gaucher disease - ophthalmoplegia - cardiovascular calcification or Gaucher-like disease). "In Gaucher disease, increased sclerostin levels have been associated with skeletal manifestations, including bone pain, bone marrow infiltration, and Erlenmeyer flask deformities." (PMID 41367909, 2025). "Since sclerostin acts as an inhibitor of Wnt/β-catenin signaling, these data suggest sclerostin as a therapeutic target for bone loss in Gaucher disease." (PMID 33779549, 2021). "In Gaucher disease, an altered sclerostin/DKK-1 ratio has been found to correlate with decreased bone mineral density, suggesting its potential utility as a biomarker of skeletal involvement." (PMID 41367909, 2025). "In a related study, sclerostin’s role as a potential biomarker for Gaucher Disease (GD) was investigated, with particular focus on its influence on the Wnt/β-catenin signaling pathway." (PMID 39727804, 2024). "Sclerostin is a canonical Wnt/β-catenin antagonist; therefore, the increased sclerostin levels observed here in Gaucher disease iPSCs are likely to lead to the previously reported decrease in β-catenin activation and osteoblast differentiation." (PMID 33779549, 2021). "We also link dysfunctional lysosomes to aberrant sclerostin regulation using human Gaucher disease iPSCs." (PMID 33779549, 2021). "Using Gaucher disease as a model system, this work links lysosomal function to sclerostin regulation in disease." (PMID 33779549, 2021). "Finally, we link sclerostin degradation not only to skeletal physiology in mice but also to human disease using Gaucher disease iPSCs." (PMID 33779549, 2021). "Having defined sclerostin regulation by the lysosome, we probed the clinical relevance using induced pluripotent stem cell (iPSC)-derived osteoblasts from Gaucher disease, a lysosomal storage disorder in which patients lack the lysosomal hydrolase glucocerebrosidase (GCase)." (PMID 33779549, 2021). "Additionally, targeting sclerostin may be important to interventions to improve bone mass in lysosomal storage disorders, like Gaucher disease." (PMID 33779549, 2021). "Likewise, we showed that restoring expression of the missing hydrolase, glucocerebrosidase, in Gaucher disease iPSCs lowers sclerostin abundance, which could explain the rescue in β-catenin activation and osteoblast differentiation reported previously." (PMID 33779549, 2021). "Consistent with lysosomal degradation of sclerostin, we observed that iPSC-derived osteoblasts from Gaucher patients had significantly increased levels of sclerostin compared to iPSC-derived osteoblasts from healthy patients without Gaucher disease." (PMID 33779549, 2021).
heart failure (4 papers, 2020 to 2025). Inability of the heart to pump blood at an adequate rate to meet tissue metabolic requirements. "Research on men with heart failure revealed significantly higher levels of osteoprotegerin, while sclerostin levels were significantly lower compared to controls." (PMID 40636828, 2025). "It needs to be added that a decrease in BMP4 content after physical activity in tibia in the group of heart failure mice only, might potentially result from an increase in sclerostin level." (PMID 32319199, 2020). "However, the impact of regular physical activity on the sclerostin concentration in heart failure condition still remains unknown." (PMID 32319199, 2020). "As a negative regulator of TGF‐β/BMP and Wnt/β catenin pathways, sclerostin is involved not only in bone remodeling, but also (through TGF‐β and Wnt signaling) might play a role in the adverse cardiac remodeling, particularly in the progression of heart failure." (PMID 32319199, 2020).
hypercortisolism (4 papers, 2019 to 2024). "Increased fracture risk and decreased bone mineral density in hypercortisolism is mainly due to suppression of bone formation, which is negatively regulated by an osteocyte-produced factor: sclerostin." (PMID 31543864, 2019). "One study documented reduced sclerostin levels in those with endogenous hypercortisolism compared to healthy controls, whereas another reported increased sclerostin levels." (PMID 38679740, 2024). "Other studies comprising healthy patients treated with prednisone for a shorter period or patients with endogenous hypercortisolemia reported a glucocorticoid-related decrease in sclerostin concentrations." (PMID 36407318, 2022). "The regulation of sclerostin shows variations in individuals with hypercortisolism." (PMID 38679740, 2024). "Interestingly, in mice, glucocorticoids stimulate the production of sclerostin, whereas circulating sclerostin was decreased in the only available study in patients with Cushing's syndrome to date during hypercortisolism, and increased after correction of glucocorticoid excess." (PMID 31543864, 2019). "Some authors also suggest, that chronic hypercortisolemia affects the number and function of osteocytes, cells that are the main source of sclerostin, rather than affects directly sclerostin concentration." (PMID 36407318, 2022).
hyperphosphatemia (4 papers, 2021 to 2025). Abnormally high level of phosphate in the blood. "In animals with high PTH levels, the efficacy of anti-sclerostin antibody was compromised, likely due to PTH suppressing SOST (sclerostin gene) expression, interference with Wnt receptor, or the effects of hyperphosphatemia and increased FGF23." (PMID 38496297, 2024). "This could be due to increased extraosseous production of sclerostin and Dkk-1 and hyperphosphatemia, increased calcitonin exposure, and absent renal clearance of both molecules." (PMID 34603797, 2021).
liver cirrhosis (4 papers, 2019 to 2025). "The behavior of sclerostin in liver cirrhosis has been studied by some researchers, yielding disparate results." (PMID 35807755, 2022). "In a recent study, higher circulating sclerostin levels were observed in patients with advanced liver cirrhosis than in healthy controls or patients with early liver cirrhosis." (PMID 31480433, 2019). "Cross-sectional studies on liver cirrhosis demonstrate correlations between disease progression and alterations in the osteocyte lacunar network along with serum sclerostin levels, with disrupted osteocyte lacunar architecture and elevated serum sclerostin concentrations in cirrhotic patients." (PMID 40735673, 2025).
malnutrition (4 papers, 2017 to 2025). Inadequate nutrition resulting from poor diet, malabsorption, or abnormal nutrient distribution. "A second aim is to assess the influence of NHD on the biomarkers fibroblast growth factor-23 and sclerostin which are thought to be associated with malnutrition and mortality in patients on haemodialysis." (PMID 28460640, 2017). "The association between sclerostin and an anorexigenic hormone such as leptin may indicate that sclerostin plays a role as a risk factor of developing malnutrition in CKD patients." (PMID 36675692, 2022). "Despite the lack of statistical significance of these associations, their negative direction may suggest that increased sclerostin levels can be a possible cause of nutritional derangements and the development of malnutrition in the population of non-dialysis CKD patients." (PMID 36675692, 2022).
neuroblastoma (4 papers, 2013 to 2025). Neuroblastoma (NB) is the most common solid, extracranial childhood tumor. "SOST encodes a secreted glycoprotein that is similar in sequence to the differential screening‐selected gene aberrative in neuroblastoma (DAN) family of bone morphogenetic protein (BMP) antagonists." (PMID 40605263, 2025). "Sclerostin is a secreted cysteine-knot protein of the differential screening-selected gene aberrant in the neuroblastoma (DAN) family, which includes proteins that antagonize BMP and Wnt signalling." (PMID 23918298, 2013). "Sclerostin is a secreted glycoprotein possessing a C-terminal cysteine knot-like (CTCK) domain and sequence similarity to the differential screening-selected gene aberrative in neuroblastoma (DAN) family of bone morphogenetic protein (BMP) antagonists." (PMID 36880646, 2023).
osteonecrosis (4 papers, 2020 to 2024). A none disease characterized by death of bone tissue due to a lack of blood supply. "Thus, we cautiously assume that usage of sclerostin antibody for patients at high risk of osteonecrosis or patients with osteonecrosis appears to be a viable treatment." (PMID 39342093, 2024). "SOST knockout not only ameliorated the incidence of osteonecrosis, but showed a net gain in bone metabolism, that is bone formation exceeds bone resorption during bone development, growth and remodeling." (PMID 39342093, 2024). "In GA-ONFH rat model, SOST knockout ameliorated the incidence of osteonecrosis and improved bone metabolism compared with the wild type group through histological, immunohistochemical and bone metabolic analyses." (PMID 39342093, 2024). "Patients with severe radiological imaging of osteonecrosis or patients at the post-collapse stage appeared with statistically significant lower sclerostin expression." (PMID 35160258, 2022). "Sclerostin was highly concentrated in osteonecrosis patient sample in the necrotic area." (PMID 39342093, 2024). "Additionally, sclerostin expression in the bone sections of femoral heads with osteonecrosis was significantly reduced compared to controls." (PMID 35160258, 2022). "Our study provides strong evidence that sclerostin played an important role in the development of GA-ONFH and blocking sclerostin secretion could improve bone turnover and ameliorate occurrence of osteonecrosis." (PMID 39342093, 2024). "In the current study, we synthesized nanocellulose (NCF)-collagen (Col)-nano hydroxyapatite (NHA) organic-inorganic hybrid aerogels loaded with stromal cell derived factor-1 (SDF-1) and sclerostin monoclonal antibody (SOST McAb) and investigated their ability to repair steroid-induced osteonecrosis." (PMID 35372296, 2022). "In patients with nontraumatic osteonecrosis of the femoral head, serum sclerostin levels were lower than controls, and the decrease was related to the stage of osteonecrosis, meaning the higher the stage, the lower the levels of serum sclerostin that were measured." (PMID 35160258, 2022).
osteopetrosis (4 papers, 2016 to 2022). Osteopetrosis, also known as marble bone disease, is a descriptive term that refers to a group of rare, heritable disorders of the skeleton characterized by increased bone density on radiographs. "Here lack of sclerostin leads to osteopetrosis indicating that it is a negative regulator of bone growth." (PMID 27558933, 2016).
Renal Dysfunction (4 papers, 2014 to 2021). "A more modest elevation was observed for SOST, but markedly higher levels were found in scrub patients with renal dysfunction or who died, and correlated strongly with markers reflecting monocyte/macrophage activation in these sub-groups." (PMID 33914733, 2021).
rheumatic disease (4 papers, 2012 to 2023). "Previous studies have linked variation in the expression of DKK1 by synovial fibroblasts to rheumatic diseases associated with excessive bone formation, primarily AS although abnormal expression of the osteocyte-specific protein (and Wnt signalling inhibitor) sclerostin has also been described." (PMID 23079210, 2012). "To date, only a few publications have investigated the role of sclerostin as a potential biomarker in rheumatic diseases." (PMID 37834893, 2023).
sclerosing bone dysplasia (4 papers, 2014 to 2025). "Sclerostin is an important bone protein, strongly associated with different bone sclerosing dysplasias." (PMID 33419004, 2021).
thyrotoxicosis (4 papers, 2012 to 2024). A hypermetabolic syndrome caused by the elevation of thyroid hormone levels in the serum. "We demonstrated that restoration of an euthyroid state after treatment of thyrotoxicosis is associated with a significant decrease of sclerostin, osteocalcin, and CTX serum concentrations coinciding with an increase of PTH concentrations." (PMID 26366174, 2015). "It has also been noted that when thyroid hormone concentrations fluctuate (e.g., thyroid hormone excess), sclerostin levels are high, and after treatment of thyrotoxicosis, sclerostin concentrations decrease." (PMID 38672114, 2024). "Previously it has been shown that after the successful treatment of thyrotoxicosis, the level of serum sclerostin decreases." (PMID 36407318, 2022). "Restoration of a euthyroid state in patients with thyrotoxicosis results in a significant decrease in serum sclerostin concentrations." (PMID 23146624, 2012). "Serum sclerostin was measured by immunoassay at diagnosis of thyrotoxicosis and after 6–10 weeks of treatment with thiamazole." (PMID 23146624, 2012). "The aim of the study was to evaluate sclerostin concentrations in patients before and after treatment of thyrotoxicosis." (PMID 23146624, 2012). "We demonstrated high levels of sclerostin in thyrotoxicosis and a significant decrease of its serum concentrations coinciding with restoration of an euthyroid state." (PMID 23146624, 2012). "Therefore, an issue of precise mechanisms that mediate changes in sclerostin concentrations during treatment of thyrotoxicosis requires further study." (PMID 26366174, 2015). "Nevertheless, all patients achieved biochemical euthyroidism, so these data are in our opinion suitable for a preliminary study, given that changes of sclerostin during treatment of an acute phase of thyrotoxicosis had not been described before." (PMID 26366174, 2015).
acromegaly (3 papers, 2022 to 2024). Acromegaly is an acquired disorder related to excessive production of growth hormone (GH) and characterized by progressive somatic disfigurement (mainly involving the face and extremities) and systemic manifestations. "The aim of the presented study was to determine SCL, OPG, and RANK-L concentrations in patients with acromegaly with regard to the disease activity and to evaluate the association between sclerostin concentrations and OPG/RANK-L system, GH, IGF-1, and BMD." (PMID 39741885, 2024). "Since sclerostin and bone fragility are linked in the general population, sclerostin became a potential target for therapy, also in acromegaly." (PMID 34448099, 2022). "Significantly lower sclerostin concentrations were observed in acromegaly patients compared with CG (AA, CTA, CA, CTA+CA, AA+CTA+CA vs CG; p < 0.001)." (PMID 39741885, 2024). "When compared to controls, acromegaly patients had significantly lower sclerostin levels, after adjustments for age and BMI (adjusted β = −36.0 ± 8.1, p < 0.001), with comparable results for both sexes." (PMID 34448099, 2022). "Median sclerostin concentration in controlled acromegaly patients was significantly lower than in healthy controls (104.5 pg/mL (range 45.7–234.7 pg/mL) vs 140.0 pg/mL (range 44.8–401.6 pg/mL), p < 0.001)." (PMID 34448099, 2022). "Further longitudinal studies are needed to establish the course of sclerostin levels during the different phases of acromegaly to elucidate its exact effects acromegalic bone disease." (PMID 34448099, 2022). "As concerns the role of RANK/RANK-L/OPG and DKK-1/sclerostin systems in acromegaly, many aspects remain to be clarified." (PMID 36362602, 2022). "This study demonstrated significantly lower plasma sclerostin levels in patients with long-term well-controlled acromegaly compared to healthy controls." (PMID 34448099, 2022). "During the last year, several research groups investigated sclerostin levels in relationship to disease activity and fractures in acromegaly, showing contradictory results." (PMID 34448099, 2022). "Patients with long-term controlled acromegaly have lower plasma sclerostin levels than healthy controls, as a reflection of decreased osteocyte activity." (PMID 34448099, 2022). "Not only the level of sclerostin values differed significantly across studies when compared between patients in different acromegaly phases and healthy controls, also the direction of associations between sclerostin and GH/IGF-1 levels was highly variable." (PMID 34448099, 2022). "Patients with acromegaly have lower sclerostin concentrations than healthy controls, which may be a result of a compensatory mechanism to increased bone loss." (PMID 39741885, 2024). "A different reason for lower SCL in acromegaly may be osteocyte dysfunction, which results in reduced synthesis of sclerostin." (PMID 39741885, 2024). "Median sclerostin concentration in controlled acromegaly patients was 104.5 pg/mL (range 45.7–234.7 pg/mL), showing comparable levels between men and women (110.0 pg/mL (range 70.0–219.2 pg/mL) in men vs 101.6 pg/ml (range 45.7–234.7 pg/mL) (p = 0.430) in women)." (PMID 34448099, 2022). "The main aim of the current study was to investigate plasma sclerostin levels in a unique cohort of long-term biochemically controlled acromegaly patients in comparison to healthy controls, and, within patients with acromegaly, to assess the potential relationship between sclerostin, BMD and VFs." (PMID 34448099, 2022). "As bone turnover is affected in acromegaly, sclerostin could be an interesting player in the alteration of bone quality in acromegaly." (PMID 34448099, 2022). "Available literature on sclerostin levels during active acromegaly also reports contradictory data, showing inconsistent associations between sclerostin and GH/IGF-1 levels, ranging from positive to negative correlations." (PMID 34448099, 2022).